ACAT1 (acetyl-CoA acetyltransferase 1)
Diseases named in the same sentence as ACAT1 in open-access papers (continued):
Sharing a sentence is not in itself a finding about the gene and the disease.
Obesity (11 papers, 2012 to 2026). Accumulation of substantial excess body fat. "Immunoblot analysis on monocytes from the same subjects showed that obesity was associated with increased ACAT1 levels and elevated histone H3 and H4 acetylation." (PMID 39841826, 2025). "Recently, report indicates that ACAT1-mediated fatty acid oxidation is associated with increased histone acetylation, and the levels of ACAT1 and histone acetylation are abnormally elevated in patients with obesity." (PMID 39454957, 2024). "Comorbidities such as obesity, hyperlipidemia, diabetes, hypertension and hyperthyroidism are known to alter the cholesterol metabolism; therefore, we analyzed the influence of BMI and comorbidities on the associations between ACAT1 or CE levels and EOC." (PMID 35399074, 2022). "We have previously reported that in a mouse model, A1B reduces inflammatory responses in adipose tissue macrophages and protects against diet-induced obesity by genetic inactivation of Acat1/Soat1 in the myeloid." (PMID 36982689, 2023). "The genotype of SCARB1 TT interacted with overweight/obesity to increase PP levels, whereas the genotypes of ACAT-1 AA and CC interacted with overweight/obesity to decrease PP levels." (PMID 23109900, 2012). "ACAT-1 AA genotype interacted with overweight/obesity to decrease PP, AC genotype interacted with overweight/obesity to increase SBP, and CC genotype interacted with overweight/obesity to decrease SBP and PP." (PMID 23109900, 2012). "In the present study, we showed that the genotypes of ACAT-1 AC, LIPC GA and AA, and SCARB1 TT interacted with overweight/obesity to increase SBP levels, whereas the genotype of ACAT-1 CC interacted with overweight/obesity to decrease SBP levels." (PMID 23109900, 2012). "Given the association of obesity with disrupted lipid metabolism and low-level inflammation, we aimed to investigate whether the T1IFN pathway, modulated by ACAT1, is constitutively activated by obesity." (PMID 39841826, 2025). "Moreover, in human subjects with obesity, circulating monocytes exhibited higher levels of ACAT1 compared to lean control subjects." (PMID 39841826, 2025). "Collectively, these findings suggest that ACAT1-mediated histone acetylation on the transcriptional regulation of T1IFN pathway could be operational in patients with obesity." (PMID 39841826, 2025). "In patients with obesity, levels of ACAT1 and histone acetylation are abnormally elevated." (PMID 38410425, 2024). "Interestingly, exposure to 4-HNE (known to be increased with obesity) increases expression of ACAT1, which is activated by cholesterol." (PMID 37106728, 2023). "The genotypes of ACAT-1 AC, LIPC GA and AA, and SCARB1 TT; LDL-R A-A- and LIPC GA; and SCARB1 TT were interacted with overweight/obesity to increase systolic, diastolic blood pressure (SBP, DBP) and pulse pressure (PP) levels; respectively." (PMID 23109900, 2012). "The genotypes of ACAT-1 CC; ACAT-1 AA and CC were interacted with overweight/obesity to decrease SBP, PP levels (p < 0.01–0.001); respectively." (PMID 23109900, 2012). "Thus, our study identified a novel link between ACAT1 mediated FA metabolism and epigenetic modification on STAT1/2 that uncovers a regulatory role of lipid metabolism in innate immune signaling and opens novel avenues for interventions in human diseases such as obesity." (PMID 38410425, 2024). "In a study comparing obese women with or without type 2 diabetes, gene expression of ACAT1 was downregulated in the VAT and ASAT of obese women with type 2 diabetes and expression was restored after bariatric surgery and weight loss, suggesting a role in obesity-associated insulin resistance." (PMID 35773277, 2022).
hepatocellular carcinoma (10 papers, 2021 to 2025). A malignant tumor that arises from hepatocytes. "ACAT1-mediated acetylation of dihydroxyacetone phosphate acyltransferase (GNPAT) plays a key role in FASN stabilization to increase lipid synthesis in hepatocellular carcinoma." (PMID 36038892, 2022). "Moreover, downregulation of this enzyme reduced the tumor burden in models of hepatocellular carcinoma and acetyl-CoA transferase ACAT1 was downregulated in A549 tumors following treatment with MTDIA, and the yeast orthologues were downregulated in meu1Δ cells." (PMID 40375736, 2025). "CHA has been reported to promote the differentiation of hepatocellular carcinoma and lung cancer by regulating microRNAs 52, but we elucidated a new mechanism from the perspective of CHA regulating ACAT1." (PMID 39494339, 2024). "Hepatocellular carcinoma (HCC) was also shown to have ACAT1 overexpression." (PMID 37835481, 2023). "ABCB6, IPO7, TIMM9, FZD7, and ACAT1, the five HBV-related genes that affect the prognosis, can work as reliable biomarkers for the diagnosis of Hepatocellular carcinoma, giving a new insight for improving the prognosis, diagnosis, and treatment outcomes of HBV-type Hepatocellular carcinoma." (PMID 36685852, 2022).
lung carcinoma (10 papers, 2023 to 2025). "Consistently, data from tissue microassays of 305 patients with lung cancer showed that TLS were more abundant in non–small cell lung cancer (NSCLC) tissues with lower ACAT1 expression." (PMID 40166933, 2025). "Subsequent in vitro cellular investigations demonstrated that the disruption of ACAT1 expression effectively inhibited the proliferation and invasion of Lewis lung cancer cells, thereby retarding the growth of cancer cells." (PMID 39083563, 2024). "To find out how ACAT1 is involved in the development of lung cancer we isolated RNA from the control and tumoral regions of our LUAD patients’ resectated lung tissue." (PMID 37024569, 2023). "Moreover, analysis of tumor samples from patients with lung cancer as well as TCGA datasets confirmed that TLS increased in NSCLC tissues with lower ACAT1 and correlated with better immunotherapy outcomes." (PMID 40166937, 2025). "We generated LLC and clonal KP mouse lung cancer cell lines with or without Acat1 knockdown (KD or negative control [NC]) and confirmed ACAT1 deficiency." (PMID 40166933, 2025). "A notable increase in the expression of ACAT1 was observed in non‐small cell lung cancer." (PMID 39083563, 2024). "Considering the grading of lung cancer and how the HMGCR and ACAT1 mRNA expression behaved in dependence of the single grading subgroups we found that ACAT1 expression showed a significant increase in the tumoral region of patients with G1 and G2 lung cancer." (PMID 37024569, 2023). "Collectively, ACAT1 may function as a promising therapeutic target for lung cancer." (PMID 38720812, 2024). "In both KP and LLC preclinical murine models of lung cancer, treatment with the ROS scavenger NAC overcame ACAT1-mediated inhibition of TLS and suppressed tumor growth." (PMID 40166937, 2025). "Acat1 KD improved B cell and TLS abundance and increased the sensitivity of lung cancer cells to anti-PD1 immunotherapy." (PMID 40166933, 2025). "To confirm that ACAT1 was correlated with TLS, we used an existing array constructed from 305 tissue samples of patients with lung cancer to determine the TLS counts and ACAT1 expression." (PMID 40166933, 2025). "In a cohort of patients with lung adenocarcinoma, ACAT1 has been found to be upregulated, while ABCA1 is downregulated in the lung cancer tissues." (PMID 38720812, 2024). "As expected, TLS numbers were increased in KD tumor lung cancer tissues compared with those in the control NC group, while TLS infiltration in Acat1–/– mice was not obvious." (PMID 40166933, 2025).
glioblastoma (9 papers, 2020 to 2025). The most malignant astrocytic tumor (WHO grade IV). "In glioblastoma, ACAT1 enhances cholesteryl ester synthesis to support membrane production and proliferation." (PMID 40370434, 2025). "Another selective ACAT1 inhibitor K604 has been found to impair the proliferation of U251−MG cells and inhibit Akt signaling in glioblastoma cells." (PMID 38720812, 2024). "For our studies here, we used K604, a selective inhibitor of ACAT-1, that we previously reported suppressed the proliferation of glioblastoma cells." (PMID 34680399, 2021). "Here, we uncovered a novel function of acetyl coenzyme A acetyltransferase (ACAT1) in regulating the differentiation of glioblastoma (GBM) cells." (PMID 39494339, 2024). "ACAT1 inhibitors effectively suppress tumor proliferation with elevated ACAT1 expression; conversely, diminished ACAT1 expression in the tumor microenvironment leads to MDSC accumulation, creating an immunosuppressive environment that facilitates glioblastoma progression." (PMID 40790033, 2025). "In addition to ACAT1, the other two key enzymes in ketone body metabolism, BDH1 and OXT1, are also downregulated in glioblastoma." (PMID 34485115, 2021).
colorectal cancer (8 papers, 2018 to 2025). A primary or metastatic malignant neoplasm that affects the colon or rectum. "Our systematic analysis of multiomics data and survival data from colorectal cancer (CRC) patients uncovered a novel association between mitochondrial acetyl-CoA acetyltransferase 1 (ACAT1) and NK cell infiltration that influences disease progression." (PMID 40289129, 2025). "Next, we validated the positive correlation between the protein level of ACAT1 and the abundance of tumor-infiltrating NK cells in patients with stage 1–2 colorectal cancer." (PMID 40289129, 2025). "In a disagreement, another study reported that ACAT1 were highly expressed in human colorectal cancer tissues and cell lines." (PMID 35172832, 2022). "Insulin-triggered cell proliferation and metastatic effects on colorectal cancer cells are mediated by ACAT1." (PMID 29793481, 2018). "In this research, we focused the relationship between insulin and colon cancer, and we found insulin-triggered cell proliferation and metastatic effects on colorectal cancer cells are mediated by ACAT1." (PMID 29793481, 2018). "Up-regulation of ACAT1 expression is involved in the progression of colorectal cancer (CRC)." (PMID 33903282, 2021). "In a colorectal cancer model, toll-like receptor 4 (TLR4) was shown to promote cell proliferation, migration, and invasion by increasing ACAT1 expression in HT29." (PMID 39940954, 2025). "The function of ACAT1, ALDH4A1, and FAS in colorectal cancer has been verified by previous studies, participating in the progression of CRC." (PMID 35992263, 2022). "In addition, rs189037 belongs to the eQTL of ACAT1 and ATM, which have been reported to be associated with carcinogenesis of colorectal cancer, so we speculate this genetic variant may increase the colorectal cancer susceptibility by influencing their expression." (PMID 29928473, 2018). "Nuclear ACAT1 directly acetylates lysine 146 of p50 (NFKB1), attenuating its DNA binding and transcriptional repression activity and thereby increasing the expression of immune-related factors, which in turn promotes NK cell recruitment and activation to suppress colorectal cancer growth." (PMID 40289129, 2025).
diabetes (8 papers, 2010 to 2025). "Previous clinical studies showed that mutations in the ACAT1 gene lead to ketoacidosis, Notably the role of ACAT1 in human cancer’ pathogenesis varies depending on cancer type, and its specific role in gastric cancer remains largely unknown." (PMID 39247186, 2024). "There were very few differences between the diabetes and control group in the untrained leg, where ACAT1 and PYGM were relatively more highly expressed in diabetes in type I and type IIX fibres, respectively." (PMID 40413649, 2025). "From the 33 seed proteins establishing direct relationships with diabetes proteins we find 3 (ACAT1, ACOX1 and HADH1) from the central routes of ketosis, synthesis and degradation of ketone bodies and lipid metabolism." (PMID 21143928, 2010). "There are some suggestions that ACAT1 might be increased in the setting of diabetes." (PMID 37378396, 2023).
glioma (8 papers, 2011 to 2025). A benign or malignant brain and spinal cord tumor that arises from glial cells (astrocytes, oligodendrocytes, ependymal cells). "Conversely, ACAT1 levels are decreased in renal cell carcinoma, nasopharyngeal carcinoma, and glioma." (PMID 39247186, 2024). "ACAT1 is dysregulated in renal cell carcinoma, nasopharyngeal carcinoma, and glioma compared to adjacent healthy tissues." (PMID 39247186, 2024). "Then they found that silencing ACAT1 maintained cholesterol homeostasis, and prevented brain hypertrophy and glioma trait-induced shortening of fly lifespan." (PMID 36091180, 2022). "The ketone body metabolizing enzymes 3-hydroxybutyrate dehydrogenase 1 and 2 (BDH1 and 2), 3-oxoacid-CoA transferase 1 (OXCT1) and acetyl-CoA acetyltransferase 1 (ACAT1) were expressed at the mRNA and protein level in all glioma cell lines." (PMID 21791085, 2011). "However, ACAT1 inhibits glioma tumorigenesis through catalyzing glycine decarboxylase K514 acetylation, which suggests the role of ACAT1 in tumor progression is still a matter of debate and warrants further investigation." (PMID 40166933, 2025). "By using the Gene Expression Profiling Interactive Analysis (GEPIA), an Internet-based tool containing high-throughput RNA-sequencing data (The Cancer Genome Atlas and Genotype-Tissue Expression databases), we found that ACAT1 had high expression in patients suffering from glioma." (PMID 39494339, 2024). "The “GABAergic synapse” and “Glutamatergic synapse pathways”, which promote glioma proliferation, were inhibited significantly, which might be related to the role of ACAT1 in fatty-acid metabolism." (PMID 39494339, 2024). "Here, we report that ACAT1 drives glioma differentiation by regulating choline metabolism." (PMID 39494339, 2024). "An orthotopic xenograft of U87 MG cells in the absence of ACAT1 in nude mice was employed to evaluate the differentiation effect of glioma." (PMID 39494339, 2024). "In repo>dEGFRλ,dp110CAAX flies, glia-specific knockdown of four genes essential for glial metabolism [ALDOA (Aldolase in flies), ACAT1 (CG8112), ELOVL6 (Baldspot), and LOX (Lox)] partly rescued glioma-induced phenotypes such as shorter lifespan and bigger tumor size." (PMID 36091180, 2022).
Alzheimer disease (7 papers, 2018 to 2025). A progressive, neurodegenerative disease characterized by loss of function and death of nerve cells in several areas of the brain leading to loss of cognitive function such as memory and language. "Increased ACAT1/SOAT1 expression/activity in activated macrophages has been implicated in atherosclerosis, Alzheimer’s disease, and cancer." (PMID 40603564, 2025). "For example, it has been previously observed that MAMs are altered in Alzheimer’s disease, and this correlates with higher ACAT1/SOAT1 activity and cholesterol accumulation within the MAM, similar to what is observed here." (PMID 36982602, 2023). "High levels of ACAT1/SOAT1 activity have been shown in a variety of disease conditions, including cancer, Alzheimer’s disease, and cardiovascular disease." (PMID 40603564, 2025).
beta-ketothiolase deficiency (7 papers, 2019 to 2025). "More than 70 pathogenic variants in the ACAT1 gene resulting in beta-ketothiolase deficiency have been identified." (PMID 41283373, 2025). "Beta-ketothiolase deficiency (BKTD) is an autosomal recessive disorder caused by biallelic mutation of ACAT1 that affects both isoleucine catabolism and ketolysis." (PMID 34001203, 2021). "Mutations in ACAT1 gene lead to 3-ketothiolase deficiency (3KTD)." (PMID 31921677, 2019). "Beta-ketothiolase deficiency (MIM 203750) occurs due to a mitochondrial acetoacetyl-CoA thiolase (T2; EC2.3.1.9) defect caused by mutation of ACAT1 (NG_009888, NM_000019.3), leading to the abnormal metabolism of isoleucine and ketone." (PMID 31156707, 2019).
clear cell renal cell carcinoma (6 papers, 2019 to 2025). "ACAT1 is frequently overexpressed in various types of cancer, including ovarian, prostate, pancreatic, clear cell renal cell carcinoma, and CRC, which aligns with our findings." (PMID 39940954, 2025). "Previous studies have also shown enhanced methylation of ACAT1 gene promoter in renal clear cell carcinoma and nasopharyngeal carcinoma, leading to decreased ACAT1 expression and a correlation with EMT initiation." (PMID 39247186, 2024). "A decreased ACAT1 expression was observed in high grade and stages of clear cell renal cell carcinoma, and ACAT1 expression was significantly reduced in clear cell renal cell carcinoma compared to adjacent normal kidney tissue." (PMID 36816175, 2023). "In clear cell renal cell carcinoma, HADHA overexpression inhibits tumor growth by increasing the expression of CYB5R3 or ACAT1." (PMID 38253797, 2024). "determined that ACAT1 was a negative prognostic biomarker of renal clear cell carcinoma (RCCC) by data analysis and validation using qPCR analysis and immunohistochemistry staining of specimens." (PMID 39323079, 2024).
Hepatic steatosis (5 papers, 2017 to 2025). Steatosis is a term used to denote lipid accumulation within hepatocytes. "ACAT1 regulates glycolysis and ketogenesis, its reduction will increase the level of circulating ketones and promote hepatic steatosis." (PMID 41516281, 2025). "We found that ACAT1 expression was significantly increased in the severe hepatic steatosis group, possibly due to its reduced acetylation modification." (PMID 37568219, 2023). "UBE3A regulation of ACAT1 proteinstability also bears physiological significance, as overexpressingUBE3A in the mouse liver downregulates ACAT1 protein contents, increasescirculating ketone levels, and promotes hepatic steatosis." (PMID 36920305, 2023). "Therefore, ACAT1 may be a potential marker of NAFLD, suggesting that the anti-hepatic steatosis effect of HQT is associated with regulation of ACAT1." (PMID 28293193, 2017). "Furthermore, potential important proteins, such as HADHA, ACAT1, EHHADH, were predicted to be essential regulators during the pathogenesis of fatty liver disease." (PMID 32586350, 2020). "Furthermore, this study identified potential important proteins, such as HADHA, ACAT1, and EHHADH, which may be important regulatory factors through modification of acetylation in the development of fatty liver disease in dairy cows and possible therapeutic targets for NAFLD in human beings." (PMID 32586350, 2020). "Furthermore, this study identified potential important proteins, such as HADHA, ACAT1, and EHHADH, which may be important regulatory factors being acetylation level modified in the development of fatty liver disease in dairy cows, potentially being therapeutic targets for NAFLD in human beings." (PMID 32586350, 2020).
Hyperglycemia (5 papers, 2015 to 2024). An increased concentration of glucose in the blood. "Coincidentally, biopsies from colon cancer patients have shown that hyperglycemia is associated with ACAT1, lymph node metastasis, and distant metastasis." (PMID 39344752, 2024). "Biopsies from patients with colon carcinoma showed hyperglycemia links ACAT1, lymph nodes metastasis and distant metastasis." (PMID 29793481, 2018). "Our data showed that ACAT1 gene expression was strongly enhanced in macrophages from type 1 and type 2 diabetic mice, and the amelioration of hyperglycemia by SGLT2i attenuated ACAT1 expression." (PMID 26606676, 2015).